RHOC (ras homolog family member C)
Diseases named in the same sentence as RHOC in open-access papers (continued):
Sharing a sentence is not in itself a finding about the gene and the disease.
gastric cancer (16 papers, 2012 to 2023). A primary or metastatic malignant neoplasm involving the stomach. "Furthermore, RhoC activation of STAT3 has been recently implicated in gastric cancer, with elevated RhoC and pTyr705 STAT3 observed in tumour samples." (PMID 32915198, 2020). "Ras homolog gene family member C (RhoC) is a small G protein/guanosine triphosphatase which closely linked to tumor growth, metastasis, invasion and progression or adverse prognosis in various malignancies such as head and neck, cervical and gastric cancers." (PMID 25933027, 2015). "miR10a promotes gastric cancer cell invasion through repression of HOXD10 expression that results in up-regulation of RHOC expression and activation of the AKT signaling pathway." (PMID 37582765, 2023). "Taken together, in this study, RNF180 is characterized as a tumor suppressor to inhibit tumor metastasis by reducing RhoC in gastric cancer." (PMID 33082325, 2020). "It is worth considering that, in gastric cancer cells, RhoA promotes cell proliferation and RhoC stimulates cell migration and invasion, while RhoB functions contrary to RhoA and/or RhoC." (PMID 32831016, 2020). "Other studies showed that RhoC enhanced proliferation of tumor cells, including esophageal squamous cell carcinoma and gastric carcinoma." (PMID 23382905, 2013). "Our results provide evidence that RhoC do have proliferation stimulating effect on gastric cancer cells." (PMID 23145020, 2012). "In this study, the expression level of IQGAP1 and RhoC and their biological activities in gastric cancer cell line BGC-823 were adjusted through infection with adenoviral constructs or transfection with plasmid DNA or siRNA." (PMID 23145020, 2012). "In conclusion, our results suggest that RhoC stimulates the proliferation of gastric cancer cells through recruiting IQGAP1 as an effector." (PMID 23145020, 2012). "Our previous results have documented that the expression of IQGAP1 and RhoC were increased in gastric cancer tissues and cancer cell lines." (PMID 23145020, 2012). "Previous studies have shown that RNF168 is lowly expressed in human gastric cancer tissues and can directly interact with RHOC and promote the degradation of RHOC by increasing the ubiquitination level of RHOC, thus affecting the function of gastric cancer cells." (PMID 36771081, 2023). "Similarly, RHOC is highly expressed in human gastric cancer tissues and enhances the proliferation, migration, and invasion of cells." (PMID 36771081, 2023). "This highlights how directed targeting of RNF180 to gastric cancer cells could be used to block RhoC-driven activation of STAT3." (PMID 32915198, 2020). "Considering the low expression of RNF180 in gastric cancer, efficiently inhibit RhoC expression might repress tumorigenesis and tumor metastasis and then improve the survival outcomes of patients, which still need further investigation." (PMID 33082325, 2020). "From the literature, RhoC was proposed to regulate proliferation through interaction with IQGAP1 in gastric cancer, suggesting that RhoC and IQGAP1 could stimulate the proliferation of gastric cancer." (PMID 32824461, 2020). "Furthermore, RhoC promotes the proliferation of gastric cancer cells and inflammatory breast cancer (IBC) and regulates apoptosis of hepatocellular carcinoma cells." (PMID 26673619, 2016). "To primarily explore the downstream mechanism through which RhoC/IQGAP1 regulate the proliferation of gastric cancer cells, we investigated the effect of RhoC/IQGAP1 on the expression of cell cycle related proteins, including cyclin E, cyclin D1, cyclin B and cyclin dependent kinase (CDK)." (PMID 23145020, 2012). "In conclusion, these data from current study, in conjunction with previously published data, support the hypothesis that RhoC participates in both migration and proliferation of gastric cancer cells." (PMID 23145020, 2012). "The results showed that RhoC also promoted the proliferation of gastric cancer cells BGC-823." (PMID 23145020, 2012).
gastric cancer (continued). "In addition, the expression and function of BCL6 in gastric cancer could be strengthened by the RNF180/RhoC pathway." (PMID 37060074, 2023). "It was reported that gastric cancer cell invasion could be induced via activation of the RhoA/ROCK pathway by IL-6, and RhoA and RhoC siRNA gene therapy mediated by adenovirus has been suggested as useful for inhibiting the growth and invasion of human gastric carcinoma via the PI3K/Akt pathway." (PMID 25238232, 2014). "It was shown that overexpression of RNF180 in gastric cancer cells can reduce STAT3 activation, attributed to increased RhoC proteasomal degradation." (PMID 32915198, 2020). "Ectopic expression of RhoA promotes proliferation and RhoC overexpression enhances motility and invasiveness of SGC7901 and AGS human gastric cancer cell lines, while RhoB overexpression suppresses these malignant phenotypes." (PMID 32392742, 2020). "The results showed that constitutively active RhoC significantly promoted the proliferation activity of gastric cancer cell line BGC-823, and depletion of RhoC by siRNA inhibited the traits." (PMID 23145020, 2012). "Herein we reported the proliferation stimulating effect of RhoC and IQGAP1 on gastric cancer cells and the interaction between two proteins in regulating the proliferation of gastric cancer cells." (PMID 23145020, 2012). "Our previous study showed that the higher expressions of RhoC and IQGAP1 in gastric cancer tissue were significantly reversely correlated with the differentiation of the gastric cancer cells." (PMID 23145020, 2012). "The results showed that RhoC, IQGAP1 and the C-terminal fragment of IQGAP1 significantly stimulated the proliferation of gastric cancer cells, and enhanced the expression of cyclin E and cyclin D1." (PMID 23145020, 2012). "Our study illustrated long non-coding RNA MIR137HG could promote the progression of gastric cancer through interacting with FUS and affecting a series of its downstream molecules (MET, RHOC, and CTNNB1." (PMID 35733138, 2022). "Gastric cancer cells have low expression of the RING finger E3 ligase, RNF180, which targets RhoC." (PMID 32915198, 2020). "In summary, our study reveals that RhoC is a substrate of RNF180 and that ubiquitination and degradation of RhoC by RNF180 could inhibit proliferation and invasion of gastric cancer." (PMID 33082325, 2020). "In recent study, RhoA and RhoC expression are elevated, while RhoB expression is downregulated or absent in gastric cancer tissues, compared to normal gastric tissues." (PMID 32392742, 2020). "Our previous research results showed that both Ras homolog family member C (RhoC) and IQ-domain GTPase-activating protein 1 (IQGAP1) were over-expressed in gastric cancer tissues and cells, but their role in tumorigenensis has not been addressed clearly." (PMID 23145020, 2012). "Interestingly, knockdown of IQGAP1 alone, but not RhoC, attenuated migration and proliferation of gastric cancer cells, indicating the crucial role of IQGAP1 in gastric cancer tumorigenesis." (PMID 32824461, 2020).
hepatocellular carcinoma (15 papers, 2004 to 2024). A malignant tumor that arises from hepatocytes. "On similar lines, YMO1, a protein belonging to the Yurt and mosaic family, was seen to reduce the invasion and metastatic ability of hepatocellular carcinoma cells, by targeting RhoC." (PMID 31340863, 2019). "In tongue squamous cell carcinoma and hepatocellular carcinoma (HCC) patients, higher expressions of AMFR, along with Ras homolog family member C (RhoC) and c-met coincides with increased risk of invasion and disease recurrence with low survival." (PMID 28890687, 2017). "Higher expression of RhoA, RhoC and ROCK have been correlated with increased invasion and metastasis in bladder cancer, with knockdown of RhoC inhibiting angiogenesis induced by hepatocellular carcinoma cells." (PMID 29147173, 2010). "In previous studies, knockdown of RhoC expression in a hepatoma cell line could significantly increase the percentage of interphase cells and thus inhibit cell proliferation." (PMID 33519932, 2021). "Studies on hepatocellular carcinoma (HCC) have suggested that RhoC promotes the evolution of healthy hepatocytes into malignant cells by promoting cell migration;20 this indicates that RhoC may be a new oncogene for HCC." (PMID 31062507, 2019). "In hepatocellular carcinoma (HCC), vascular channels were formed, and these vessels were associated with RhoC FAK/Paxillin signaling regulation as well as with high expression of RhoC/ROCK2, VE-cadherin, and MMP2 mediated by ERK/MMPs signaling." (PMID 31993365, 2019). "RhoC and its effector ROCK2 have been shown to play important roles in this context by activation of the ERK and MMP pathways in the hepatocellular carcinoma model." (PMID 31340863, 2019). "Ras homologous C (RhoC) is expressed in various cancers, including hepatocellular carcinoma (HCC)." (PMID 23382905, 2013). "The sucessful tumor cell integration of these multi-functionalized nanoparticles proved to drastically suppress tumorigenesis by targeting mTOR, PAK4, RHOC, and the epithelial–mesenchymal transition (EMT) in hepatocellular carcinoma (HCC) PDX models." (PMID 35954481, 2022). "In hepatocellular carcinoma (HCC) infected with hepatitis B virus (HBV), HBs and HBx proteins induce the expression of Ets-1 transcription factor, thereby enhancing the activity of the RhoC promoter to upregulate RhoC expression." (PMID 34627249, 2021). "There were a number of limitations present in this study, including the use of Huh7 cells derived from a hepatoma, the lack of a secondary proteomic assay for GNB1, and the use of RHOA/RHOC antibody instead of a RHOC-specific antibody." (PMID 39066215, 2024).
inflammatory breast carcinoma (15 papers, 2004 to 2024). An advanced, invasive breast adenocarcinoma characterized by the presence of distinct changes in the overlying skin. "RhoC overexpression was especially linked to aggressive cancers as for example inflammatory breast cancer, which metastasizes rapidly." (PMID 29152087, 2017). "RhoC overexpression has been associated with inflammatory breast cancer and may be involved in tumor angiogenesis." (PMID 19703301, 2009). "Our previous work showed that RhoC regulates inflammatory breast cancer migratory responses to macrophage conditioned media." (PMID 31214501, 2019). "As RhoC is frequently upregulated in inflammatory breast cancer, we intended to analyze its potential for inducing EMT, migration and invasion and to regulate specific genes involved in tumorigenesis." (PMID 29152087, 2017). "This is contrary to what we had demonstrated for RhoC-mediated migration and invasion in inflammatory breast cancer." (PMID 15969750, 2005). "SUM 149 was compared to a control cell line, SUM 102, which was selected because it shares a deletion in the LIBC (lost in inflammatory breast cancer) gene with the SUM 149 cell line but reportedly expresses RhoC mRNA at low levels." (PMID 15857504, 2005). "Interestingly, the over-expression of RhoC has been reported in inflammatory breast cancer and exclusively in invasive breast carcinoma." (PMID 24533098, 2014). "The metastatic influence of RhoC is exemplified by inflammatory breast cancer (IBC)." (PMID 22911725, 2012). "Thus, our work reveals both a role for the microenvironment in tumor-associated macrophage secreted cytokines and lends further support for RhoC as a potential target for therapeutic intervention aimed at preventing the metastasis of inflammatory breast cancer." (PMID 27991524, 2016). "This is of particular interest in inflammatory breast cancer, as recent findings from our lab show SUM-149 cells are heavily glycolytic, heavily dependent on glutamine for survival, and SUM-149 metabolism is regulated by RhoC." (PMID 31214501, 2019).
lung cancer (13 papers, 2010 to 2024). A malignant neoplasm involving the lung. "The overexpression of RhoC has been reported to be involved in regulating tumor cell proliferation, invasion and metastasis, including lung cancer." (PMID 38725025, 2024). "Upon JMJD8 knockdown in lung cancer cell lines, cyclin B1, RhoA, RhoC, MMP9, and N-cadherin were down-regulated, and p21 and E-cadherin were conversely up-regulated." (PMID 33442397, 2021). "In the human lung cancer cell line, A549, lumican was found to promote cell proliferation by increasing the expression of Ras homolog gene family, member C (RhoC) and phosphorylated protein kinase B (p-Akt)." (PMID 31963522, 2020). "Therefore, western blot and real-time PCR analyses were used to detect the expression of RhoA, RhoB, and RhoC in A549, H446 lung cancer cells transfected with plasmid Prox1 and interfering siRNA." (PMID 34183992, 2021). "In order to assess whether RhoA is required for K-Ras-induced lung cancer initiation, we utilized the K-RasG12D Lox-Stop-Lox murine lung cancer model in combination with a conditional RhoAflox/flox and RhoC-/- knockout mouse models." (PMID 26030593, 2015). "Recent findings have confirmed that in lung cancer cells, siRNA-TMEM98 significantly suppressed the invasion and migration of human A549 and H460 cells through down regulating MAT1, MMP-2, MMP-9 and RhoC." (PMID 29152140, 2017). "For instance, induced RhoC expression did not have any effect on tumor growth in orthotopic lung cancer in mice." (PMID 29854771, 2018). "This suggested that downregulation of RhoC might not decrease OSCC cell proliferation, which is also consistent with studies using mouse models of lung cancer." (PMID 33519932, 2021).
pancreatic cancer (12 papers, 1998 to 2023). "HIF-3α was found to be overexpressed in pancreatic cancer, especially under hypoxic conditions promoting metastasis by activation of the ras homolog family member C/Rho associated coiled-coil containing protein kinase (RhoC-ROCK) pathway." (PMID 33466454, 2021). "RhoC is a small GTPase which is an important effector of tumor cell motility and is expressed in pancreatic tumors." (PMID 25188245, 2014). "We demonstrate, in this report, a direct involvement of RhoC with trafficking and signaling of integrin α5β1 in invading pancreatic cancer cells." (PMID 24312560, 2013). "We also report that RhoC and integrin α5β1 co-localize within the peri-nuclear region of pancreatic tumor cells, and by masking the CAAX motif at the C-terminal of RhoC protein, we were able to abolish this interaction in vitro and in vivo." (PMID 24312560, 2013). "Here, we confirm that RhoC significantly enhances the migratory and invasive properties of pancreatic carcinoma cells." (PMID 24312560, 2013). "Our results provide evidence that both RhoA and RhoC are the targets of BITC in pancreatic cancer cells." (PMID 22016776, 2011). "Thus, expression of RhoC protein in metastatic regions of pancreas cancer was reported to be higher than that of the primary tumor lesions." (PMID 23382905, 2013). "Thus, in contrast to pancreas carcinomas, rhoC mRNA expression level seems not to be an indicator of malignancy in breast tumours." (PMID 12237774, 2002). "These suggest that elevated expression of the rhoC gene may be involved in the progression of pancreatic carcinoma independent of K-ras gene activation." (PMID 9459160, 1998).
glioma (11 papers, 2010 to 2025). A benign or malignant brain and spinal cord tumor that arises from glial cells (astrocytes, oligodendrocytes, ependymal cells). "At the same time, RHOC is also a member of RHOC/Cofilin signaling pathway, and several genes can be involved in glioma mechanism by regulating this signaling pathway." (PMID 37239411, 2023). "Circ-EPB41L5 inhibits the proliferation, migration, and invasion of glioma cells by sponging miR-19a-3p and regulating the host gene EPB41L5 expression, which reduces the progression of glioma by inhibiting RhoC and p-AKT." (PMID 33946718, 2021). "circ-EPB41L5 inhibited the proliferation, migration, and invasion of glioma cells by sponging miR-19a and regulating the expression of the host gene EPB41L5 that suppressed the progression of glioma by inhibiting RhoC and p-AKT." (PMID 31905344, 2020). "Expression levels of urokinase receptor (uPAR) and Ras homolog gene family member C (RhoC) were found to be directly proportional to that of miR-10b, thereby enhancing the invasive capabilities of high-grade glioma." (PMID 23054677, 2013). "Rescue experiments indicated that HSP90B1 might facilitate glioma migration, invasion, and radiotherapy resistance by modulating RhoC expression." (PMID 41716636, 2025). "In glioma cells, miR-10b regulates the expression of mRNA for RhoC and urokinase-type plasminogen activator receptor (uPAR) via inhibition of translation of the mRNA encoding homeobox D 10 (HOXD 10), resulting in invasion and metastasis of glioma cells." (PMID 21176238, 2010). "Additionally, HSP90B1 might enhance glioma metastasis and resistance to radiotherapy by regulating RhoC expression." (PMID 41716636, 2025). "The direct target of miR-10b, which is probably involved in the invasion of gliomas, includes Homeobox 10 (HOXD10), which negatively regulates the urokinase type plasminogen activator receptor (uPAR) and RhoC (RAS homolog family member C)." (PMID 35330864, 2022). "Previous studies have demonstrated that RhoC phosphorylates AKT via activating ROCK1, and phosphorylation of AKT plays a critical role in the development of glioma." (PMID 31905344, 2020). "Taken together, circ-EPB41L5 affected the proliferation, migration, and invasion of glioma cells by regulating the miR-19a-EPB41L5, RhoC, and p-Akt signaling pathways." (PMID 31905344, 2020). "This includes effects on cell invasion (RAC1, RAC2, RAC3, RHOA, RHOC), focal adhesion formation (RHOA), stemness of glioma precursor cells (RAC1), cell proliferation (RAC1, RND3) and cell cycle (RND3)." (PMID 26132659, 2015). "Seven Rho GTPases (RND1, RND3, RAC3, RHOA, RAC2, RAC1 and RHOC) showed a significantly greater connectivity in grade IV glioma and seven (CHP, RHOD, RHOF, RHOB, RHOQ, RND2, RHOBTB3) showed greater connectivity in grade II glioma." (PMID 26132659, 2015).